LDHB (lactate dehydrogenase B)
Diseases named in the same sentence as LDHB in open-access papers (continued):
Sharing a sentence is not in itself a finding about the gene and the disease.
tumor (continued). "Although genetic disruption or silencing of LDHA was shown to inhibit tumor growth in vitro and in vivo in several studies, it has been suggested that only disruption of LDHA and LDHB together can abolish the growth of tumor cell lines in vitro." (PMID 31781212, 2019). "Although an essential role of LDHB in the progression of various cancers has been increasingly reported, how LDHB is precisely controlled in glycolytic regulation and tumor progression remains poorly understood." (PMID 31804482, 2019). "In case of GW5074 treatment, ectopic expression of either LDHB WT or K329Q resulted in comparable tumour volumes and weights." (PMID 30443978, 2019). "The results indicated that FGFR1, MYPT1, and LDHB are relevant to disease progression, i.e., FGFR1 is negatively correlated with tumor progression whereas MYPT1 and LDHB are positively correlated with tumor progression in tumor-adjacent stroma." (PMID 31316912, 2019). "Although the expression of LDHB is slightly less than LDHA in DLD1 and HeLa cells, LDHB is indispensable for high level of glycolysis and tumor progression." (PMID 31804482, 2019). "Statistical analysis of the protein expression indicated that in tumor-adjacent stroma FGFR1 and MYPT1 were significantly correlated with patient outcomes and LDHB showed the outcome-association tendency." (PMID 31316912, 2019). "Apart from the undisputed role of LDHA and LDHB in tumor cell metabolism and adaptation to unfavorable environmental or cellular conditions, these enzymes participate in the regulation of cell death." (PMID 31035592, 2019). "Together, we demonstrated that Aurora-A phosphorylates LDHB at Ser162, facilitating glycolysis and biosynthesis to promote tumor growth." (PMID 31804482, 2019). "To further establish the expression relationship between miR-375 and LDHB, we compared miR-375 and LDHB mRNA expressions in a series of 54 MCC tumor samples." (PMID 30441870, 2018). "The results are consistent with previous studies supporting that LDHB promotes tumor development and progression." (PMID 30441870, 2018). "Identical findings were recently obtained on the same two cell lines by a double gene disruption of LDHA/LDHB that fully suppressed fermentative glycolysis with a minimal effect on tumor growth (Maša Ždralević and Jacques Pouysségur, unpublished data)." (PMID 29152106, 2017). "In tumor tissue sections, LDHB and G6PC staining revealed their utility as new biomarkers to discriminate embryonal from fetal components of tumors." (PMID 28923827, 2017). "In non‐tumor liver, LDHB was moderately expressed in the cytoplasm and nucleus of interlobular bile duct cells, but never in hepatocytes." (PMID 28923827, 2017). "LDHA has shown to be overexpressed in many cancers and to play a crucial role in tumour proliferation, invasion and metastasis whereas the role of LDHB remains more elusive." (PMID 28680592, 2017). "Pyruvate fermentation to lactate via LDH was more complicated with LDHA and LDHAL6B being increased in tumor tissues (2.55 and 0.69 log2 fold-change, respectively), while LDHB and LDHAL6A were decreased (-2.11 and -0.24 log2 fold-change, respectively)." (PMID 27128972, 2016). "In mouse immortalized cell lines, LDHB is critical in the mechanistic target of rapamycin (mTOR) pathway to induce tumor formation." (PMID 25652794, 2015). "LDHB is also considered as a tumor marker that increases in many cancers because it facilitates tumor growth and cell proliferation." (PMID 25652794, 2015). "LDHA is overexpressed in many cancers and plays a crucial role in tumor proliferation, invasion, and metastasis, whereas the role of LDHB depends on different types of tumors and remains more elusive." (PMID 26426634, 2015). "Lactate dehydrogenase B (LDH-B) is upregulated in tumor endothelium, and VEGF signaling increases glycolytic flux by inducing GLUT1 and the glycolytic enzyme 6-phosphofructo-2-kinase/fructose-2,6-bisphosphatase-3 (PFKFB3)." (PMID 25063693, 2014).
tumor (continued). "Taking advantage of two primary human MCC cells lines established in our laboratory as well as fresh MCC tumor samples, we measured the expression of LDHB and hnRNPF at the mRNA level." (PMID 25284964, 2013). "In vivo, LDHB inhibition reduced tumor growth and enhanced cisplatin’s therapeutic efficacy." (PMID 40790017, 2025). "In summary, in this study, we aimed to investigate whether LDHB silencing can inhibit tumor growth in PM per se and further augment the anticancer activity of cisplatin treatment." (PMID 40790017, 2025). "In a study currently under consideration for publication elsewhere, we showed that tumor growth of A549 xenografts is significantly delayed by LDHB silencing and completely blocked when LDHB silencing is combined with a single local irradiation with 10 Gy of ionizing radiation." (PMID 40158058, 2025). "Therefore, further studies using orthotopic tumor models in immunocompetent hosts will be essential to understand how targeting LDHB affects tumor growth within an intact tumor immune microenvironment." (PMID 40790017, 2025). "Cisplatin treatment reduced tumor growth over time to a similar extend than LDHB silencing." (PMID 40790017, 2025). "However, only the combination of RT and LDHB deletion resulted in complete suppression of tumor growth during the experimental period." (PMID 40090955, 2025). "Despite the high structural conservation between LDHA and LDHB, their distinct biological functions and expression across tumor types suggest that designing subunit-selective inhibitors offers a promising strategy for developing clinically viable LDH inhibitors." (PMID 41226160, 2025). "Furthermore, CD63 exhibited significantly higher expression levels in the malignant cell clusters of immune cells and demonstrated a strong correlation with glycolytic genes, such as LDHA and LDHB, in tumor cells." (PMID 41573746, 2025). "Finally, radiation therapy induces mitochondrial lipid peroxidation and reduces tumor growth, which is further enhanced when combined with LDHB silencing." (PMID 40090955, 2025). "Future studies are needed to determine the extent to which DNA damage or lipid peroxidation contributes to the observed anti-tumor effects of LDHB silencing and whether these contributions vary across different tumor types." (PMID 40790017, 2025). "For example, LDHB exhibits tumor-promoting effects in pancreatic cancer, breast cancer, lung cancer, and colorectal cancer, while demonstrating tumor-suppressive activity in prostate cancer and liver cancer." (PMID 41226160, 2025). "Next, we aimed to test the effect of LDHB silencing on tumor growth in vivo." (PMID 40790017, 2025). "The siRNA-based silencing of LDHB significantly reduced LDHB protein expression, resulting in decreased formation of colonies and tumor spheres, proliferation and cell viability in three PM cell lines with different LDHB basal protein levels, i.e., MSTO-211H, MESO4 and H2052." (PMID 40790017, 2025). "Lactate dehydrogenase A (LDHA) and LDHB are essential metabolic products that promote tumor growth." (PMID 38764020, 2024). "Finally, to evaluate the relationship between the antitumor immune response and LDHB level in tumor tissues, infiltrated CD8+ T cells in paraffin­embedded tumor tissues were detected using immunofluorescence assay." (PMID 38739169, 2024). "We also revealed that DNA methyltransferase DNMT3A could silence LDHB expression and restoring LDHB expression might suppress HCC progression through remodeling the tumor immune microenvironment." (PMID 38739169, 2024). "Our findings indicate that DNMT3A-mediated epigenetic silencing of LDHB may contribute to HCC progression through remodeling the tumor immune microenvironment, and LDHB may become a potential prognostic biomarker and therapeutic target for HCC immunotherapy." (PMID 38739169, 2024). "Taken together, these results suggested that LDHB may regulate HCC progression by remodeling the tumor immune microenvironment." (PMID 38739169, 2024).
tumor (continued). "Interestingly, decreased LDHB has recently been found to be involved in tumor immune regulation in breast cancer." (PMID 38739169, 2024). "Currently, the roles of LDHB in tumor development are not fully understood." (PMID 38739169, 2024). "In addition, LDHB was involved in maintaining the antitumor activity of tumor infiltrating dendritic cells." (PMID 38739169, 2024). "Additionally, the estrogen/GPER/PKA/LDHB/lactate axis in CAFs induces tumour cells to express ASCT2 and GLS1, enhancing the absorption and utilization of GPER‐induced glutamine in TNBC." (PMID 39690134, 2024). "The results showed that P300, LDHA and LDHB were all overexpressed in tumor samples." (PMID 37950222, 2023). "Then, retrospective IHC analysis revealed that the expression levels of LDHA and LDHB were significantly associated with tumor grade, stage, size, and OS, which indicated that enhanced LDHA and decreased LDHB were positively correlated with ccRCC aggressiveness." (PMID 37547725, 2023). "Since MCT1 might be associated with uptake of extracellular lactate, which will be further transformed into pyruvate within tumor cell by LDHB." (PMID 36814318, 2023). "Phosphorylated LDHB reduces the inhibition of substrates in the reduction reaction, significantly accelerates the conversion of pyruvate to lactate, and promotes the glycolysis and proliferation of tumor cells." (PMID 37582735, 2023). "Notably, also LDHA/LDHB expression ratio—measured within each tumour sample—shows a marked increase only in BRAF-like tumours, whereas LDHB is modestly upregulated in the RAS-like subtype." (PMID 37198319, 2023). "Studies have shown that the overexpression of LDHB in T cells enhances their respiration and cytokine production when exposed to lactic acid, a byproduct of anaerobic glycolysis that is commonly elevated in the tumor microenvironment." (PMID 37508430, 2023). "Finally, it should be marked that the detailed mechanism between LDHA/LDHB and tumor immune needs further clarification." (PMID 37547725, 2023). "Further TIMER2 and TISIDB databases analysis manifested the close relationship between LDHA/LDHB expression and immune infiltrates (including immune cells and immune inhibitors) in >500 ccRCC patients, which indicates the complex tumor microenvironment (TME) of ccRCC." (PMID 37547725, 2023). "This suggests that simultaneous inhibition of LDHA and LDHB could attenuate tumor aerobic glycolysis." (PMID 37576895, 2023). "Both LDHA and LDHB were associated with tumor immune infiltrates in ccRCC patients, which suggested LDHA/LDHB could be implicated in the tumorigenesis of ccRCC and might be potential therapeutic targets for patients with ccRCC." (PMID 37547725, 2023). "In contrast, LDHB was expressed in peripheral and invasive tumor areas." (PMID 36278433, 2022). "Although LDHB exerts a reverse function which convert lactate to pyruvate under physiological conditions, a recent study revealed that Aurora-A mediated phosphorylation of LDHB S162 markedly enhances its catalytic activity to convert pyruvate to lactate and promotes glycolysis and tumor progression." (PMID 35669414, 2022). "In silico analysis on a single‐cell RNAseq database from invasive and central GB areas demonstrated a similar pattern, with preferential expression of LDHA in the central area and LDHB in the peripheral area albeit mRNA of both enzymes was found in a portion of invasive tumor cells." (PMID 36278433, 2022). "Thus, our research revealed that LDHB is essential to maintain mitochondrial DNA integrity and mitochondrial metabolism, which is crucial for tumor-initiating cells and tumorigenesis." (PMID 35877003, 2022). "This suggests, that LDHB overexpression in T cells could be beneficial for their anti-tumor activity and probably improve outcome of ACT treatment approaches." (PMID 35682650, 2022).
tumor (continued). "An LDH inhibitor (GSK 2837808A, potently inhibiting both LDHA and LDHB) abrogated the increase in cytokine production in the presence of lactate, indicating an active lactate-to-pyruvate enzymatic conversion activity in this tumor-like metabolic environment." (PMID 35452600, 2022). "The results indicated that knockdown of LDHB significantly inhibited tumor growth." (PMID 35669414, 2022). "In addition, LDHB expression had different effects on different tumors, promoting or inhibiting tumor growth." (PMID 35978348, 2022). "The discrepancy of LDHB on glycolysis and tumor progression may result from different cell lines were used and different oxygen concentration." (PMID 35669414, 2022). "Thus, LDHA and LDHB had a distinct spatially restricted expression pattern in the tumor core but were found both expressed in invasive cells." (PMID 36278433, 2022). "Hence, LDHA is a promising predictor of poor prognosis and a target for anticancer therapy, whereas the significance of LDHB in tumor development is still elusive." (PMID 36612084, 2022). "In colorectal carcinoma, deacetylated LDHB promotes autophagy and tumor growth." (PMID 36551514, 2022). "Genetic disruption or silencing of LDHA and LDHB in tumor cells inhibits tumor growth." (PMID 34394085, 2021). "Since functional consequences of LDHB in MΦ are unknown, we expected that downregulating LDHB by miR-375 and subsequent lactagenesis may have consequences not only for TAMs but also tumor cells." (PMID 34158867, 2021). "LDHB is silenced by promoter hypermethylation in some cancer types, while in others, it is highly expressed and involved in the aggressive progression of tumor." (PMID 33792181, 2021). "Importantly, in tumor sections showing high miR-375 amounts, LDHB was barely expressed in TAMs and vice-versa." (PMID 34158867, 2021). "The metabolic model of lactate shuttling in the tumour microenvironment is known as metabolic symbiosis in tumours, where LDHB is a key molecule of the oxidative pathway of lactate that controls metabolic symbiosis between glycolytic and oxidative cancer cells." (PMID 34725423, 2021). "In addition to LDHA, the activity of lactate dehydrogenase B (LDHB), which also supports the conversion of lactate to pyruvate, is frequently upregulated in tumor cells and can thereby mediate therapy resistance." (PMID 34359663, 2021). "We hypothesized that in TAMs the presence of the antagomir should prevent tumor-derived miR-375 binding to LDHB, thereby enhancing LDHB expression and reducing lactate formation." (PMID 34158867, 2021). "Lactate dehydrogenase B (LDHB) has been revealed to act as a tumor promoter in several cancers." (PMID 32484203, 2020). "Moreover, MCT1 expression in tumor cells showed a strong positive correlation with LDHB expression in TNBC tumors, corroborating the presence of the reverse Warburg effect." (PMID 33324565, 2020). "Inhibitors targeting LDHB are likely to inhibit the growth of tumour cells." (PMID 32391634, 2020). "Although the substrate preference of LDHA and LDHB differs, these observations indicate that substrate affinity and the extent of metabolic adaptation in tumors may vary depending on both tumor-specific intrinsic and extrinsic cues." (PMID 33324565, 2020). "In addition to their widespread expression in normal tissues, LDHA and LDHB are often overexpressed in tumor tissues, including TNBC." (PMID 33324565, 2020). "The role of LDHA and LDHB in tumor biology is more complex than was initially expected." (PMID 31035592, 2019). "While reintroduction of RNAi-resistant LDHB-WT and LDHB-S162D fully restored cell growth, LDHB-S162A expression failed, suggesting that LDHB S162 phosphorylation is required for the rapid proliferation of tumor cells." (PMID 31804482, 2019). "This supports the evidence that the non-mutated LDHB gene is potentially a critical aspect within tumor sample 810CL." (PMID 31484939, 2019).
tumor (continued). "Significantly, low levels of LDHB‐Ac‐K329 in tumours may predict short survival time in patients with CRC." (PMID 30443978, 2019). "However, our results indicated that LDHB was positively correlated with tumor progression in tumor-adjacent stroma, which was also opposite to the previous study in tumor tissues." (PMID 31316912, 2019). "Interestingly, the level of LDHB can strongly differ even in the cell lines established from the same tumor type (e.g., PANC-1 vs. CaPan-1 pancreatic cells)." (PMID 31035592, 2019). "Given that the MCPyV small T-antigen can promote a pro-glycolytic phenotype, the question arises whether the viral oncoprotein could change the cellular metabolism of the cells that converts LDHB from its oncogenic role to tumor suppressor." (PMID 30441870, 2018). "We found that the nuclear score for RPS7 was negatively correlated with HIF-1α, GLUT4 or LDHB staining in tumor tissues (p < 0.05), evidenced by the representative images showing the high expression of RPS7 corresponding to the low expressions of HIF-1α, GLUT4 or LDHB in same tissues, or vice versa." (PMID 26735579, 2016). "The tumor suppressor drs regulates glucose metabolism via LDHB." (PMID 26918353, 2016). "To confirm whether the expression of RPS7 can up-or down-regulate HIF-1α, GLUT4 and LDHB in vivo, we performed IHC analyses on tumor sections from all the experimental groups." (PMID 26735579, 2016). "Decreased LDHB expression might enhance negative regulation of the Warburg effect, which mediates pyruvate into lactate and back in tumor cells." (PMID 25652794, 2015). "Results showed that the growth inhibition varied in the range of 3.32% to 39.42%, suggesting that the effect of LDHB knockdown on tumor progression might be dependent on its basal level in tumors." (PMID 25973606, 2015). "The significance and the regulation of LDHB expression in cancer development remains unclear, but different tumor phenotypes may originate from the alteration of LDHA and LDHB caused by mutation, chromosomal deletion/duplication, and increase of copy number." (PMID 25372838, 2014). "The correlation between protein and mRNA levels for LDHA and LDHB was less relevant, but related to previous studies on cell metabolism where a mix between aerobic and anaerobic glycolysis was described in normal and tumor cells." (PMID 23516535, 2013). "The role of LDHB in tumor development is less well characterized." (PMID 23516535, 2013). "Increased expression of LDHB in MCCs suggests increased tumor metabolism depending on glycolysis in energy demand and further implies the idea that MCCs are sensitive to perturbation in the end stage of glycolysis-lactate production, and thus open a therapeutic window in the clinics." (PMID 25284964, 2013). "Therefore, it would be valuable to investigate whether silencing LDHB renders cancer cells from additional tumor types more sensitive to cisplatin and other DNA-damaging treatments, such as radiotherapy." (PMID 40790017, 2025). "Thus, it would be valuable to explore whether inhibition of LDHB can enhance the efficacy of RT in immunocompetent tumor models." (PMID 40158058, 2025). "Similarly, enforced expression of LDH isoforms can affect T cell fate: a recent report indicates that overexpression of LDHB (which enhances lactate-to-pyruvate flux) in tumor-specific CD8+ T cells improves their function in the lactate-rich tumor microenvironment." (PMID 40710349, 2025). "Moreover, LDHB plays a key role in tumor metabolic cooperation or “metabolic symbiosis”, wherein oxidative cancer cells preferentially oxidize lactate produced by glycolytic tumor cells, conserving glucose for hypoxic regions within the tumor microenvironment." (PMID 40733189, 2025). "Thus, targeting LDHB could be a promising strategy to enhance the effectiveness of chemotherapy-based combination therapies for PM and potentially other tumor types." (PMID 40790017, 2025).